RN7SKP236 (RN7SK pseudogene 236)
Gene: Miscellaneous RNA gene on chromosome 21 (25,101,132 to 25,101,415, forward strand). Ensembl gene ENSG00000274662.
Homologues: Orthologues: chimpanzee 7SK (99% identical). Paralogues in human: RN7SKP71 (80% identical), RN7SKP180 (79% identical), RN7SKP255 (79% identical), RN7SKP203 (78% identical), RN7SKP9 (78% identical), RN7SKP176 (78% identical), 7SK (77% identical), RN7SKP38 (77% identical), RN7SKP184 (77% identical), RN7SKP246 (77% identical), RN7SKP171 (76% identical), RN7SKP239 (76% identical), and 284 more.